ST20-MTHFS (ST20-MTHFS readthrough)
Gene: Protein-coding gene on chromosome 15 (79,845,150 to 79,923,754, reverse strand). Ensembl gene ENSG00000259332.
Genetic constraint (gnomAD): Loss-of-function variants: 5 observed, 12.71 expected, observed/expected ratio (o/e) 0.39, 90% interval 0.2 to 0.83. The upper end of that interval is the gene's LOEUF score, 0.83, which puts it in group 3 of 6, group 1 being the genes least tolerant of losing a copy. Missense variants: 182 observed, 213.45 expected, observed/expected ratio (o/e) 0.85, 90% interval 0.75 to 0.96. Synonymous variants: 72 observed, 76.4 expected, observed/expected ratio (o/e) 0.94, 90% interval 0.78 to 1.15.